MCM2 (minichromosome maintenance complex component 2)
Diseases named in the same sentence as MCM2 in open-access papers (continued):
Sharing a sentence is not in itself a finding about the gene and the disease.
cancer (continued). "Furthermore, we combined the results of the perturbation-induced reversal effects on the expression levels of MCM2 and MCM10 and the sensitivity correlation between perturbations and MCM2 and MCM10 from the Cancer Therapeutics Response Portal database." (PMID 35056094, 2021). "In most types of cancer (except for adipose, bone, and tooth cancers), the expression of MCM2 and MCM10 was higher in cancerous tissues than non-cancerous tissues." (PMID 35056094, 2021). "A previous study showed that the high expression of MCM2, MCM5, and MCM7 might indicate a poor prognosis of cancer." (PMID 34413873, 2021). "In addition, H2AFX, MCM2, MCM7, and POLD1 were highly up-regulated in 31 cancer tissues, based on the analysis of TCGA data." (PMID 33442399, 2021). "Similar to the effect of the ubiquitination-resistant mutant of Geminin, expression of cancer-derived SPOP mutants also increased Cdt1 binding to MCM2, CDC6, and ORC2 but had no influence on Geminin binding to Cdt1." (PMID 34599168, 2021). "MCM2 and MCM6 are the upstream transcription factors regulating the ORC1 protein factor and are upregulated in the case of cancer; therefore, it could provide some explanations for the upregulation of ORC1." (PMID 32193399, 2020). "The researchers concluded that high expression of MCM2, MCM5, and MCM7 might be prognostic indicators for poor outcomes in cancers." (PMID 32089988, 2020). "Some of LINC00094 target PCGs have well‐known functions in cancer, including BATF3, SCG2, and MCM2." (PMID 32460441, 2020). "Finally p‐STAT3, Mcm2, and MSR1 were used to construct the model for predicting cancers in the repeat biopsy cohort." (PMID 32860339, 2020). "Indeed, in our study, strong correlations emerged between MCM-2 or MCM-5 LIs and the conventional proliferation index Ki-67, which remained even after stratification of our cases into borderline or carcinoma categories." (PMID 17940502, 2007). "Thus, origin specification and excess MCM2–7 loading on origins do not require the six-subunit ORC in human cancer cell lines." (PMID 40530691, 2025). "Higher MCM2 level was resistant to nine drugs or small molecules, such as Trametinib, and sensitive to 27 drugs, such as NPK76-II-72-1, suggesting that MCM2 may be a potential biomarker for drug screening across cancers." (PMID 35693940, 2022). "Secondly, given that MCM2 is highly expressed in several types of cancers (including PDAC), and that MCM2 has a much longer half-life as compared to other proliferation markers (e.g. Ki-67), it might take more time before the inhibitory effects of UAMC-2526 on MCM2 expression are visible." (PMID 34868951, 2021). "Besides, H2AFX, MCM2, MCM7, and POLD1 were highly up-regulated in 31 cancer tissues." (PMID 33442399, 2021). "In addition, CDC20, CDK4, MCM6, MAD2L1, MCM2 and MCM5 were leading genes intersecting in these four pathways, and a positive correlation between mRNA expression and LACTB was observed in most normal and cancer tissues." (PMID 33507917, 2021). "In addition, the results revealed a significantly lower MCM-2 level in the advanced stage of cancer in both recurrent and non-recurrent subgroup analyses." (PMID 34272446, 2021). "Furthermore, some studies report that MCM2 has no independent relevance for cancer-specific survival." (PMID 32089988, 2020). "Furthermore, certain cell cycle–related proteins, including TOP2A, PCNA, MCM2, MCM4, MCM5, MCM6, and MCM7, have also been reported to facilitate cancer cell proliferation, and the enhanced expression of these cell cycle–related proteins may contribute to uncontrolled ESCC cell proliferation." (PMID 38652547, 2024). "The increase in MCM2 expression observed after DXR treatment indicated that cell cycle arrest did not occur and that the cancer cells were actively proliferating." (PMID 31370818, 2019).
cancer (continued). "Paraffin sections of 41 OED cases that progressed to carcinoma, 40 OED without malignant progression, 38 OSCC and 15 NOM were immunostained with antibodies against Mcm2, geminin and Ki67." (PMID 19293805, 2009). "Moreover, BIRC-5, KNTC-1, MCM2, MKI-67, PCNA, and E2F4 genes were downregulated in HCT-116 cancer cell lines, and there was no significant change in the expression of the same genes in HT-29 cancer cell lines." (PMID 40872562, 2025). "The top-ranked genes by NGP-PLK1, MCM2, MCM3, MCM7, MCM10 and SKP2 might coordinate to promote cell cycle related processes in cancer but not normal cells." (PMID 22838965, 2012). "Our results suggest that the top-ranked genes by NGP-PLK1, MCM2, MCM3, MCM7, MCM10 and SKP2 might coordinate to promote cell cycle related processes in cancer but not normal cells." (PMID 22838965, 2012). "In addition, several of these genes have not previously been reported as methylated in any type of cancer (KCNK4, SEPT5, PENK, BMP4, TAL1, PGF, SMARCB1 (INI1), FRZB (SFRP3), IRAK3 and MCM2)." (PMID 19493342, 2009).
infection (10 papers, 2012 to 2024). The state of being infected such as from the introduction of a foreign agent such as serum, vaccine, antigenic substance or organism. "The knockdown of MCM2 led to increased viral replication during infection, suggesting that MCM2 serves as a restriction factor for HBV proliferation." (PMID 36661536, 2023). "The results suggested that MCM2 should be involved in HBV entry/establishing an infection or cccDNA accumulation in the internal cycle, and that the MCM2 should serve as a restriction factor for HBV replication." (PMID 36661536, 2023). "This is exemplified by the expression pattern of the proliferation markers Ki67 (Mki67), Pcna, Ccna2 and the minichromosome maintenance complex genes Mcm2 and Mcm6, which peak late in infection (Cell Cycle panel)." (PMID 38107402, 2023). "Indirect immunofluorescence co-labelling of MCM2 and the LT-Ag revealed that infection with BKPyV triggered a significant increase in the proportion of MCM2 positive cells and that significantly fewer cells became MCM2 positive in the presence of IFNγ." (PMID 35194151, 2022). "At the protein level MCM2 was significantly induced by BKPyV-infection (p < 0.001) and that increase was significantly suppressed by IFNγ (p < 0.01)." (PMID 35194151, 2022). "We infected MDM with VSV‐G‐pseudotyped HIV‐1 and 48 h post‐infection stained the cells for MCM2 or for EdU incorporation (added at the time of infection) to monitor active DNA synthesis and analysed cells by using an automated microscopic system." (PMID 28122869, 2017). "Critically, degradation of SAMHD1, through co‐infection with SIVmac VLP‐vpx, or SAMHD1 depletion using RNAi, completely abrogated the association between infection of MDM and MCM2 expression (and EV4C)." (PMID 28122869, 2017). "We infected these cells with VSV‐G‐pseudotyped HIV‐1 and at 48 h post‐infection inspected the cells for specific macrophage markers F4/80 and CD11b, as well as expression of MCM2 and EdU incorporation." (PMID 28122869, 2017). "Mcm2 expression was higher in C3H mice than in C57BL/6 mice, and Mcm2 expression was elevated by FLV-infection." (PMID 22768239, 2012). "Since SCF activity is required to degrade cell cycle inhibitors that may block viral replication, we also inhibited licensing by using siRNAs to knockdown MCM2-7 prior to a BKPyV infection." (PMID 39636788, 2024). "Mcm2 and Cyclin D1 were amplified in c-Junf/f mice as well as in c-JunΔli mice upon infection." (PMID 37990129, 2023). "We found that the gene products encoded by ARID1A, PLEC and HDAC4 but not MCM2 were specifically decreased following infection with VSV∆51-amiR-4 as shown by RT-qPCR and immunoblotting analysis." (PMID 35393414, 2022). "Furthermore, in C3H mice, the spleen Mcm2 levels were elevated by FLV-infection." (PMID 22768239, 2012). "IFNγ exposure reduced mean MCM2 and MKI67 transcript expression in BKPyV-infected cultures compared with infection alone but, due to the variance in the IFNγ-response, these changes were not statistically significant." (PMID 35194151, 2022). "Critically, and as before, we observed preferential infection of MCM2‐positive cells from WT but not SAMHD1 negative cells." (PMID 28122869, 2017). "We found that infection did not significantly alter MCM2 levels compared to mock-infected cells." (PMID 35216024, 2022). "Indeed, log odds ratios comparing frequencies of HIV‐1 infection in MCM2‐positive and MCM2‐negative cells were high, indicating highly specific infection of MCM2‐positive cells, but not MCM2‐negative cells." (PMID 28122869, 2017).
adenocarcinoma (6 papers, 2007 to 2025). A common cancer characterized by the presence of malignant glandular cells. "Gene expression levels of MCM2/3/4/6 were also specifically elevated in human NEPC when compared to adenocarcinoma CRPC19,20." (PMID 34172788, 2021). "We quantitated MCM2 levels in the glandular adenocarcinomas, the component with the greatest similarity to the autochthonous model." (PMID 33821796, 2021). "A key feature of the signature, up-regulation of Ube2c, Mcm2, and Fen1, was validated in mouse normal lung and adenocarcinoma tissues and cells by immunohistochemistry and western blotting, respectively." (PMID 20686609, 2010). "Because gene expression at the mRNA level does not always correspond to protein levels, we then examined the expression of the protein products of Ube2c, Fen1 and Mcm2 in Gprc5a−/− lung normal and adenocarcinoma tissue and cells." (PMID 20686609, 2010). "Functional pathways analysis using the IPA® software revealed significant modulation of neighborhood and network gene modules surrounding the Mcm2 and Fen1 genes in the Gprc5a−/− adenocarcinoma (top and bottom, respectively)." (PMID 20686609, 2010). "Using comparative functional genomics and functional pathways analysis followed by validation at the protein level by immunohistochemistry and western blotting analyses, we highlighted the marked up-regulation of Ube2c, Mcm2 and Fen1 in Gprc5a-knockout mouse adenocarcinoma relative to normal lung." (PMID 20686609, 2010). "In accordance, Mcm2, Fen1, Ube2c and cyclin D1 proteins were also relatively higher in the MDA-F471 mouse adenocarcinoma cells compared to the normal Gprc5a−/− cells as revealed by the western blotting analysis." (PMID 20686609, 2010). "We found that MAPK inhibition failed to reduce the MCM2 rate in control adenocarcinomas, whereas the MCM2 rate declined in tumors with Cyclin D2 knockdown upon RAF/MEK inhibitor treatment." (PMID 33821796, 2021). "Within both the LMP and adenocarcinoma groups MCM-5 (but not MCM-2)-positive cells tended to outnumber Ki-67-positive cells (Wilcoxon's signed rank paired test P=0.0300 and 0.0206, respectively)." (PMID 17940502, 2007). "Within the adenocarcinomas only, MCM-5 (but not MCM-2) protein expression was also related to the histologic type (Kruskal–Wallis ANOVA, P=0.0349), the highest levels of immunoreactivity being recorded in poorly differentiated and nonspecified categories." (PMID 17940502, 2007).
benign neoplasm (1 paper, 2023). A neoplasm which is characterized by the absence of morphologic features associated with malignancy (severe cytologic atypia, tumor cell necrosis, and high mitotic rate). "More intense MCM2 staining in PTC than benign tumors as demonstrated in our study is a novel finding, but we found that MCM2 is unable to differentiate between PTC TNM stages." (PMID 36676734, 2023).
colon (1 paper, 2021). "Interestingly, the downregulated DEGs, such as MAD2L1, CCNA2, MCM2, MCM4, FEN1, and CDK6, were enriched in DNA replication, tyrosine metabolism, and cell cycle pathways, which are commonly upregulated in colon cancer." (PMID 34521988, 2021).
MCM2 also shares sentences with these, for which no sentence is quoted: cholangiocarcinoma (4 papers); oral epithelial dysplasia (3); acute lymphocytic leukemia (2); acute myeloid leukaemia (2); follicular adenoma (2); follicular carcinoma (2); invasive carcinoma (2); thyroid carcinoma (2); acinic cell carcinoma (1); ameloblastic carcinoma (1); ampullary carcinoma (1); angiosarcoma (1); benign breast disease (1); brain cancer (1); brain tumours (1); Candidemia (1); cervical tumors (1); chondrosarcoma (1); Clear Cell Renal Cell Carcinoma (1); colorectal adenocarcinoma (1); colorectal tumors (1); Cornelia de Lange syndrome (1); dedifferentiated liposarcoma (1); diabetes (1); endocervical adenocarcinoma (1); endometrial carcinoma (1); endometrial endometrioid adenocarcinoma (1); endometrial mixed adenocarcinoma (1); endometrial serous adenocarcinoma (1); endometrioid carcinoma (1).
A further 35 diseases each share a sentence with MCM2 in 1 paper.